SAA2 (serum amyloid A2)
Description:
Major acute phase reactant.
Synonyms: SAA
Tractability: Antibody: UniProt places it where antibodies can reach, with medium confidence; UniProt predicts a signal peptide or a membrane-spanning region; its Gene Ontology location is reachable by antibodies, with medium confidence.
Gene: Protein-coding gene on chromosome 11 (18,239,223 to 18,248,668, reverse strand). Ensembl gene ENSG00000134339.
Subcellular location: Secreted
Gene Ontology:
Molecular function: protein binding
Cellular component: extracellular exosome; extracellular region
Genetic constraint (gnomAD): Loss-of-function variants: 7 observed, 10.84 expected, observed/expected ratio (o/e) 0.65, 90% interval 0.37 to 1.21. The upper end of that interval is the gene's LOEUF score, 1.21, which puts it in group 5 of 6, group 1 being the genes least tolerant of losing a copy. Missense variants: 94 observed, 136 expected, observed/expected ratio (o/e) 0.69, 90% interval 0.58 to 0.82. Synonymous variants: 49 observed, 52.07 expected, observed/expected ratio (o/e) 0.94, 90% interval 0.75 to 1.19.
Homologues: Orthologues: chimpanzee SAA2 (98% identical), macaque SAA1 (89% identical), macaque SAA2 (87% identical), zebrafish saa (59% identical), Drosophila melanogaster CG30467 (10% identical). Paralogues in human: SAA1 (93% identical), SAA4 (55% identical), SAAL1 (20% identical).
Diseases named in the same sentence as SAA2 in open-access papers:
SAA2 is named in the same sentence as 82 diseases in open-access papers, as found by Europe PMC text mining. Sharing a sentence is not in itself a finding about the gene and the disease. The quoted sentences say what the papers report.
COVID-19 (28 papers, 2020 to 2026). A disease caused by infection with severe acute respiratory syndrome coronavirus 2. "MALDI-TOF analysis revealed differential plasma levels of SAA1 and SAA2 associated with higher risk of hospitalization and can be used to improve COVID-19 monitoring and therapy." (PMID 34168074, 2021). "SAA2, for example, is linked to inflammation and tissue (e.g., cancer cell lines) injury and has been identified as a biomarker of severe COVID-19 and poor prognosis." (PMID 37662846, 2023). "In this regard, recent studies reported an impaired interferon signaling response in tracheal aspirates of patients with severe COVID-19, which may serve as a mechanism underlying reduced SAA2 stimulation in the lower respiratory tract of COVID-19 patients with ARDS." (PMID 34441862, 2021). "We also observed that plasma from PLWH with COVID-19 had the greatest multiplicative increase in SAA2 (FC = 139.28) and SAA1 (FC = 110.40); however, this difference was not statistically significant after FDR correction." (PMID 40568587, 2025). "Several proteins linked to the acute phase response, such as CRP, SERPINA3, SAA1 and SAA2, have been shown to increase in the plasma of patients with severe COVID-19 using MS-based data-independent analysis." (PMID 40568587, 2025). "ROC analysis showed ideal AUC values for SAA1 (0.912) and SAA2 (1.000) in patients with COVID-19-induced ARDS." (PMID 37197655, 2023). "Among these proteins, only serum amyloid A (SAA2) was increased by 12-fold in COVID-19 patients, showing statistical significance (p = 0.04)." (PMID 36430724, 2022). "The SAA1 and SAA2 proteins were also identified up-regulated in severe COVID-19 patients in a clinical cohort from China." (PMID 34168074, 2021). "Intriguingly, this is on par with our AutoML findings in that SAA2 can be used as a predictor of the severe prognosis in patients with COVID-19." (PMID 34302024, 2021). "The SAA2 has been used to monitor the severity of COVID-19 and as a biomarker for SARS-CoV-2 infection." (PMID 34566994, 2021). "The ROC curve showed that SERPINA3 could only distinguish between influenza, COVID-19, Mix, and health; SAA1 could only distinguish between COVID-19, Mix, and health; and SAA2 could only distinguish between influenza and health." (PMID 40158620, 2026). "To determine whether SERPINA3, SAA1, and SAA2 can serve as biomarkers for influenza, COVID-19, and Mix, we classified the three genes." (PMID 40158620, 2026). "Validation of SERPINA3, SAA1, and SAA2 as biomarkers for influenza, COVID-19, and Mix." (PMID 40158620, 2026). "Notably, SAA2 emerged as an important biomarker of influenza infection compared with healthy individuals and COVID-19 infected individuals." (PMID 40158620, 2026). "Improved large-scale shotgun approaches combined with extensive fractionation have been applied to identify potential COVID-19 biomarkers and could be used in association with SAA1 and SAA2 provided in this study to create a panel of more reliable biomarkers." (PMID 34168074, 2021). "A distinctive finding using this approach was the acute-phase response SAA2–SAA4 (SAA2–4) readthrough proteins, whose overrepresentation was associated with nonsevere and severe COVID-19 patients." (PMID 34566994, 2021). "Additionally, the acute phase proteins (CRP, SAA1 and SAA2) deviated from the linear correlation (R2 = 0.97) of the plasma proteome changes quantified in both genders, indicating a 3- to 6-fold difference in concentrations measured six months after COVID-19." (PMID 39183264, 2024). "However, the increase in the expression of SAA2–4 coding acute-phase reactant genes or serum protein levels has not been directly associated with COVID-19 patients but with clear cell renal carcinoma and lung cells." (PMID 34566994, 2021).
COVID-19 (continued). "ROC curve analysis shows that SERPINA3 can distinguish influenza, COVID-19, mixed infection and healthy people; SAA1 can distinguish COVID-19, mixed infection and healthy people; SAA2 can distinguish influenza and healthy people." (PMID 40158620, 2026). "Serum amyloid A1 (SAA1) and serum amyloid A2 (SAA2), which were significantly upregulated in both the acute and subacute phases, have been reported to be severity-related biomarkers in ARDS due to COVID-19." (PMID 40375315, 2025). "We found that the expression levels of inflammation-related proteins (CRP, SAA1, SAA2, and ORM1) were substantially elevated in the acute phase of COVID-19, consistent with the proteomic results." (PMID 38965561, 2024). "For these COVID-19 convalescents, we found higher plasma concentrations of CRP, SAA1, and SAA2 six months after COVID-19." (PMID 39183264, 2024). "The inflammatory factors SAA2, SAA1, SERPINA1, and SERPINA3 are significantly upregulated proteins in the sera of the severe COVID-19 patients." (PMID 38638822, 2024). "We found that the plasma levels of HP, LTA4H, S100A9, SAA1, SAA2, and SERPINA3 were significantly elevated in more severe COVID-19 conditions, exhibiting good clinical predictive value and promising applications." (PMID 37197655, 2023). "For example, acute phase proteins (APPs) including serum amyloid A-1 (SAA1), SAA2, SAA4 and C-reactive protein (CRP) were increased in severe COVID-19 patients, indicating activation of inflammation and the complement system." (PMID 35686122, 2022). "We further identified strong genetic correlations (|r| > 0.5) between smaller sets of proteins related to COVID-19 severity, and host proteins relevant to viral replication such as between IL-6-induced proteins (SAA1, SAA2, and CD14) and fibulin 5 (FBLN5)." (PMID 33328453, 2020). "Nevertheless, for the COVID-19 patients, we did find clustering based on hospitalization status (ICU, ward, or discharge), showing that the main drivers of plasma proteomes (CRP, SAA1, and SAA2) can effectively function as clinical classifiers for disease severity." (PMID 40224277, 2025). "Cluster 12 and 13 report proteins that are increased in all COVID-19 patients but at higher levels in ICU/F patients which are mainly constituted by proteins playing a role in acute inflammatory response (CRP, ORM1, ORM2, SAA1, SAA2, S100A8, S100A9, Serpin A3)." (PMID 36348270, 2022). "Moreover, most acute phase proteins, such as SAA1, SAA2, SAA4, CRP, SERPINA3, and SAP/APCS, which were increased in severe COVID-19 patients were not changed in our CoronaVac immunized samples." (PMID 35686122, 2022).
lung carcinoma (9 papers, 2011 to 2024). "Indeed, SAA2 was significantly increased in lung cancer and had effective diagnostic value in lung, endometrial and colorectal tumors." (PMID 37430202, 2023). "Consistent with the upregulation of SAA1 and SAA2 in lung cancer, a decreased level of Apo A-1, an APRP responsible for endogenous cholesterol removal from tissues, was observed in sera of adenocarcinoma patients with respect to healthy donors." (PMID 22229091, 2011). "Furthermore, Wang and colleagues noted that the aberrant expression and release of SAA2 regulated by WDR4/PML promotes lung cancer progression by increasing intertumoral Tregs and M2-like macrophages while reducing CD8+ T cell infiltration." (PMID 39457484, 2024). "Moreover, SAA1 and SAA2 seem to be also involved in lung cancer metastasis, by inducing the expression of matrix metallopeptidase-9 (MMP-9) by macrophages." (PMID 22229091, 2011). "Thus, SAA1, SAA2, and Apo A-1 could also be considered potential biomarkers for the early detection of lung cancer." (PMID 36768828, 2023). "Therefore, together with the increase in SAA1 and SAA2, the decrease in Apo A-1 could also be considered a potential lung cancer marker." (PMID 22229091, 2011). "Therefore, SAA1 and SAA2 could also represent new potential therapeutic targets for the inhibition of lung cancer metastasis." (PMID 22229091, 2011). "Among which, SAA1, SAA2, HP, NAMPT, CHI3L1 and CHI3L2 have been reported to act as tumor promoters in multiple cancers including lung cancer, breast cancer and ovarian cancer." (PMID 38763993, 2024). "In lung cancer, WDR4 degrades PML through the ubiquitination pathway and upregulates its downstream CD73, urokinase plasminogen activator receptor (uPAR) and serum amyloid A2 (SAA2) via HIF-1." (PMID 37710294, 2023).
glioma (8 papers, 2013 to 2025). A benign or malignant brain and spinal cord tumor that arises from glial cells (astrocytes, oligodendrocytes, ependymal cells). "In conclusion, an immune signature constructed using HLA-DQA2, HOXA3, and SAA2 exhibited significant and specific prognostic value for IDH1mt glioma, while the high-risk group classified by the signature had a high benefit from ICB." (PMID 36159801, 2022). "Then, via LASSO and Cox regression analyses, immune signatures were constructed using HLA-DQA2, HOXA3, and SAA2, and IDH1mt-glioma patients were divided into high-risk and low-risk groups." (PMID 36159801, 2022). "There is also evidence for association of SAA2 (serum amyloid A2) with invasiveness of glioma cells." (PMID 31487431, 2019). "In glioma, high expression of SAA2 was associated with temozolomide resistance." (PMID 36159801, 2022). "Furthermore, ROC analysis was performed to determine the diagnostic value of HLA-DQA2, HOXA3, and SAA2 in the survival of IDH1mt-glioma patients, and all showed remarkable diagnostic value (AUC = 0.832, 0.896, and 0.857)." (PMID 36159801, 2022). "We then performed a multivariate Cox regression analysis, and the immune signature constructed using HLA-DQA2, HOXA3, and SAA2 was found to act as an independent prognostic factor for glioma patients with IDH1mt, with an HR of 1.203." (PMID 36159801, 2022). "A multivariate Cox analysis also indicated that HLA-DQA2, HOXA3, and SAA2 were independent predictors of survival in glioma patients with IDH1mt." (PMID 36159801, 2022). "Therefore, the gene expression information of HLA-DQA2, HOXA3, and SAA2 and the survival information of glioma patients with IDH1mt in TCGA were imported into R software to construct a risk model." (PMID 36159801, 2022). "In this study, we focused on the IDH1mt subtype glioma and found that the risk model constructed using HLA-DQA2, HOXA3, and SAA2 showed remarkable prognostic value for IDH1mt glioma in both TCGA and CGGA cohorts but not for wtIDH1-glioma." (PMID 36159801, 2022). "IHC was performed to detect the expression of HLA-DQA2, HOXA3, and SAA2 in glioma tissues, and high expression of HLA-DQA2, HOXA3, and SAA2 was observed in glioma tissues in the short-term group compared with that in the long-term group." (PMID 36159801, 2022). "Since it is well known that CXCL12 activates members of the MAP kinase family in gliomas via its G-protein-coupled receptors CXCR4 and CXCR7, it seems obvious that CXCL12 regulated CCL2 and SAA2 expression during cellular dormancy entry via these pathways." (PMID 32346064, 2020). "Most have previously been proposed as biomarkers in a specific tumor (or tumor-related condition): C15orf48 in esophageal cancer, NF2 in neurofibromatosis, CMTM6 in renal adenocarcinoma, PLEK2 in lung adenocarcinoma, RRM2 in glioma, HOXA1 in breast and gastric cancers, and SAA2 in renal cancer." (PMID 34204789, 2021). "Because SAA is an acute-phase protein predominantly expressed and produced in the liver in response to inflammation, we tested whether these glioma cells express and produce the isoforms SAA1, SAA2, and SAA4 in basal conditions." (PMID 23533307, 2013).
Obesity (8 papers, 2010 to 2026). Accumulation of substantial excess body fat. "Although CD14, CLU, CD99, and SAA2 have been reported to be protein markers for insulin resistance, obesity, and inflammation, our data showed that they only had a modest difference in expression level between healthy and pre-diabetic sera." (PMID 33995275, 2021). "SAA1 and SAA2 are highly homologous reactants whose concentration can increase upon infection, trauma, and obesity, whereas SAA3 is a pseudogene and SAA4 is a constitutively expressed minor constituent of the nonacute-phase HDL." (PMID 20847813, 2010). "Empagliflozin may protect the heart by altering the expression of genes including Apoe, Apoc1, Saa2, Apoa2, and Pon1, which are all involved in lipid metabolism disturbance in obesity." (PMID 36242090, 2022). "SAA2 was reported to be increased in the plasma of people with obesity and insulin resistance." (PMID 33995275, 2021). "Further examination of DEPs revealed that following empagliflozin treatment, the expressions of Apoe, Apoc1, Saa2, Apoa2, and Pon1 altered dramatically, suggesting that these proteins may be the main proteins that empagliflozin uses to treat obesity-induced aberrant lipid metabolism." (PMID 36242090, 2022). "While the best defined cell source of SAA1 and SAA2 is hepatocytes, SAA1 and SAA2 are also expressed from adipocytes and macrophages under inflammatory conditions in metabolic diseases such as obesity, insulin resistance, and cardiovascular disease." (PMID 32158768, 2020). "The increased circulating SAA levels observed in individuals with obesity are highly correlated with body mass index (BMI), body weight, adiposity, and SAA1 and SAA2 mRNA expression in white adipose tissue (WAT), and are not related to hepatic SAA1 or SAA2 expression." (PMID 37396595, 2023). "Since humans do not express SAA3, SAA1 and SAA2 may be the major isoforms contributing to inflammation in human obesity." (PMID 35909571, 2022).
Sepsis (7 papers, 2020 to 2026). Sepsis is defined as life-threatening organ dysfunction caused by a dysregulated host response to infection. "Its two human isoforms, SAA1 and SAA2, are predominantly produced by hepatocytes and contribute to systemic immune responses in sepsis but also in a range of other inflammatory conditions, such as arthritis." (PMID 40595432, 2025). "Acute phase reactants, including c-reactive protein (CRP), serum amyloid A-1 (SAA1), and serum amyloid A-2 (SAA2), significantly discriminated sepsis patients from healthy controls." (PMID 40864331, 2025). "Sepsis groups showed significantly elevated levels of acute-phase reactants, including CRP, SAA1, and SAA2, reflecting the immediate immune response to infection of the host." (PMID 40864331, 2025). "SAA1;SAA2, CRP, ITIH3, SERPINA1 are acute phase proteins that are also dysregulated in other inflammatory states including sepsis." (PMID 36812516, 2022). "In agreement with the literature, peptides from ITIH3, SAA2, SAA1, and FN1 showed variation in observation frequency between ICU-Sepsis versus ICU Control." (PMID 32636717, 2020). "Peptides and/or phosphopeptides of common plasma proteins such as ITIH3, SAA2, SAA1, and FN1 showed increased observation frequency by Chi square (χ2 > 9, p < 0.003) and/or precursor intensity in sepsis." (PMID 32636717, 2020). "Differential analysis identified 6 proteins that were significantly upregulated in sepsis serum samples, including MMP9, lipocalin-2 (LCN2), serum amyloid A1 (SAA1), serum amyloid A2 (SAA2), paired-like homeobox 2B (PHOX2B), and lactoferrin (LTF) (|log2FC| > 1, P < 0.05)." (PMID 41306770, 2025).
breast cancer (6 papers, 2019 to 2025). A primary or metastatic malignant neoplasm involving the breast. "In the present study, we explore the effects of genetic deletion of SAA1 and SAA2 (hereafter referred to as SAA1-2), the two major SAA proteins in mice, on liver inflammation caused by 4T1 breast cancers." (PMID 36817472, 2023). "Furthermore, our findings indicate that the overexpression of SAA1 promotes breast cancer progression by downregulating autophagy in vitro, while the double knockout of Saa1 and Saa2 in vivo induces autophagy as a protective mechanism against cell death." (PMID 36248994, 2022). "The top four upregulated differentially expressed genes (DEGs), SAA2, UBE2C, CEMIP and ANXA8L1, have been associated with increased inflammation, cancer progression, metastatic potential and overall poor survival outcomes of various cancers including breast cancer." (PMID 39768151, 2024).
amyloidosis (5 papers, 2010 to 2026). A disorder characterized by the localized or diffuse accumulation of amyloid protein in various anatomic sites. "For example, SAA1/SAA2 are downregulated while SAA3 is upregulated during amyloidosis." (PMID 40420730, 2025). "In E. multilocularis-infected C57BL/6 mice, amyloidosis, consisting of a mixture of serum amyloid A1 (SAA1) and (SAA2)-derived AA protein was detected in the kidney, liver and spleen of the experimental animals." (PMID 21283804, 2011).
colitis (4 papers, 2018 to 2023). Inflammation of the colon. "One study showed that mice concurrently deficient in Saa1, Saa2, and Saa3 had attenuated colitis as assessed by histology." (PMID 37396595, 2023). "Similarly, mice that were deficient in Saa1 and Saa2 that had colitis-associated colon cancer showed attenuated weight loss, gut histological damage, and gut inflammation, findings that suggest that Saa1/2 may augment colitis severity." (PMID 37396595, 2023). "Although receiving RA administration, AGN‐treated mice developed more severe colitis with more Th17 cell infiltration and higher epithelial expression of Saa1, Saa2, and Cebpa, suggesting that RA could regulate C/EBPA in colitis via RARs." (PMID 37983567, 2023). "In a colitis mouse model, SAA1/SAA2 double knockout mice displayed increased weight loss, histological disease scores and TNF-α expression, suggesting that SAA1/SAA2 may provide protection at the intestinal epithelial barrier through its direct antibacterial properties." (PMID 32477346, 2020).